ADAMTS13 (ADAM metallopeptidase with thrombospondin type 1 motif 13)
Diseases named in the same sentence as ADAMTS13 in open-access papers (continued):
Sharing a sentence is not in itself a finding about the gene and the disease.
myasthenia gravis (1 paper, 2025). Myasthenia gravis (MG) is a rare, clinically heterogeneous, autoimmune disorder of the neuromuscular junction characterized by fatigable weakness of voluntary muscles. "It is a routine procedure to treat diseases like TTP that lack critical plasma components (e.g., the vWF-cleaving protease—ADAMTS13), or diseases that are characterized by pathognomonic circulating factors that need to be removed (e.g., myasthenia gravis and AChR-Ab)." (PMID 41266700, 2025).
myeloma (1 paper, 2024). "Notably, none of the patients had progressive myeloma at the time of the event and ADAMTS-13 was evaluated in two patients and was within normal limits." (PMID 39191958, 2024).
myonecrosis (1 paper, 2025). "This group of 10 patients were older and displayed a lower platelet count (which remain normal), a more intense myonecrosis along with higher fibrinogen and C-reactive protein levels compared with patients with normal ADAMTS13 activity." (PMID 41160661, 2025).
Neonatal sepsis (1 paper, 2023). Systemic inflammatory response to infection in newborn babies. "ADAMTS-13 deficiency in septic neonates is a novel finding with promising future implications, as ADAMTS-13 substitution may serve as a useful therapeutic option in neonatal sepsis, prompting further investigation in future studies." (PMID 37886991, 2023).
non-small cell lung carcinoma (1 paper, 2022). A group of at least three distinct histological types of lung cancer, including non-small cell squamous cell carcinoma, adenocarcinoma, and large cell carcinoma. "An elevated VWF/ADAMTS13 ratio was shown to be independently associated with poor prognosis and mortality in patients with advanced non-small-cell lung cancer (NSCLC)." (PMID 35327035, 2022).
parasitemia (1 paper, 2015). "ADAMTS13 antigen (ρ = −0.41, P = 0.010) and activity levels (ρ = −0.60, P = 0.0001), with all associations remaining significant after adjusting for parasitemia." (PMID 25569250, 2015). "ADAMTS13 antigen and activity levels correlated with platelet count (ρ = 0.36, P = 0.025; and ρ = 0.56, P = 0.0003, respectively), with this association remaining significant after adjusting for parasitemia." (PMID 25569250, 2015).
platelet disorders (1 paper, 2022). "Additionally, the thrombosis, inflammation, and platelet disorders may affect the ADAMTS13:AC, VWF:Ag, and Et levels in patients with LC." (PMID 35407443, 2022).
pneumococcal infection (1 paper, 2008). Infections with bacteria of the species streptococcus pneumoniae. "This review describes the forms of HUS/TTP that are not related to Shiga toxin, pneumococcal infection, genetic causes, or ADAMTS13 deficiency." (PMID 17906963, 2008).
prostate tumors (1 paper, 2022). "In this regard, a study found that forty percent of patients with prostate tumors demonstrated mild ADAM metallopeptidase with thrombospondin type 1 motif 13 (ADAMTS-13) deficiency." (PMID 36474619, 2022).
pulmonary arterial hypertension (1 paper, 2021). Pulmonary arterial hypertension (PAH) is a group of diseases characterized by mean pulmonary artery pressure >20 mmHg and elevated pulmonary arterial resistance leading to right heart failure. "Adjusted for age and sex, ADAMTS13 discriminated pulmonary arterial hypertension from the other disease groups with an AUC of 0.91 (sensitivity = 87.5%, and specificity = 78.4%)." (PMID 34616545, 2021). "Plasma ADAMTS13 in incident pulmonary arterial hypertension was lower compared to the healthy controls (p = 0.055), as well as CTEPH (p < 0.0001), HFrEF-PH (p < 0.0001), HFrEF-PH (p < 0.0001), and Dyspnoea/HF-non-PH (p < 0.0001)." (PMID 34616545, 2021).
renal carcinoma (1 paper, 2017). A carcinoma arising from the epithelium of the renal parenchyma or the renal pelvis. "Out of the unique set of genes detected by BNNPT, a few were reported to be relevant to renal cancer or disease: CDCP1, GSTT1, E2F3, MAPK1, SALL4, SIRT1, ADAMTS13, Gfrα1, ASPH, MIR17HG, APOE, BMP4, RCOR1, NUMB and SEC63." (PMID 28986523, 2017).
respiratory infections (1 paper, 2024). "An increase in plasma VWF associated with a decrease in ADAMTS-13 has been reported in respiratory infections of both viral and bacterial etiology." (PMID 39408067, 2024).
Salmonella Infections (1 paper, 2021). Infections with bacteria of the genus SALMONELLA. "Here, we present an unusual case of late-onset cTTP occurring after salmonella infection at the age of 43 years caused by homozygosity for a rare, complex ADAMTS13 allele." (PMID 33732721, 2021). "The inflammatory trigger (salmonella infection) probably caused an upregulation of endothelial VWF secretion and increase of VWF plasma levels, which caused acute flare of the disease in analogy to triggering acute TTP by shiga toxin in an ADAMTS13 deficient mouse model." (PMID 33732721, 2021).
Splenomegaly (1 paper, 2024). Abnormal increased size of the spleen. "Schematic workup for hemolytic anemia revealed negative Coomb's test, positive urine hemosiderin, normal ADAMTS13 activity, and absent splenomegaly." (PMID 38707129, 2024).
staphylococcus aureus infection (1 paper, 2024). An infectious process in which the bacteria Staphylococcus aureus is present. "Staphylococcus aureus infection has been shown to be associated with increased levels of neutrophil extracellular traps (NETs) and von Willebrand factor (VWF) and decreased ADAMTS13 activity." (PMID 39408067, 2024).
streptococcal meningitis (1 paper, 2022). An infectious meningitis caused by infection with Streptococcus. "Although his ADAMTS13 level was not suggestive of TTP, at 54.4% (normal low ADAMTS13: >66.8% activity; severe ADAMTS13 deficiency: ≤10% activity), he improved only after plasmapheresis was initiated, supporting a diagnosis of a TTP-like syndrome likely due to his streptococcal meningitis." (PMID 36465227, 2022).
TAFRO syndrome (1 paper, 2024). "Past studies reported a decrease in ADAMTS13 activity, which is crucial for fibrinolysis, in three cases with TAFRO syndrome." (PMID 38672203, 2024).
tuberculosis (1 paper, 2017). A chronic, recurrent infection caused by the bacterium Mycobacterium tuberculosis. "ADAMTS-13 concentrations were lower in patients with HIV-tuberculosis who died than in survivors, possibly owing to higher concentrations of vWF." (PMID 28363198, 2017). "Concentrations of vWF and VCAM-1 were higher in mycobacteremic patients than in patients with HIV-tuberculosis without mycobacteremia, whereas concentrations of ADAMTS-13, Ang-1, and Tie-1 were lower." (PMID 28363198, 2017).
type 1 diabetes (1 paper, 2015). "We have investigated whether von Willebrand factor, ADAMTS13 (a disintegrin and metalloproteinase with thrombospondin type 1 motif, member 13), and D-Dimer were associated with different levels of renal function in patients with type 1 diabetes." (PMID 26168189, 2015).
uremia (1 paper, 2021). A clinical syndrome associated with the retention of renal waste products or uremic toxins in the blood. "The identification of the unknown origin of ADAMTS-13 inhibitor may probably be the lost piece of the puzzle that will unveil the full picture of hemostasis in uremia." (PMID 34572522, 2021).
vasculitis (1 paper, 2020). "On day 3, activity of a disintegrin and metalloproteinase with thrombospondin type 1 motif, member 13 (ADAMTS13) activity was not significantly reduced, and clinical markers for vasculitis and connective tissue disease were negative." (PMID 32728521, 2020).
vitamin D deficiency (1 paper, 2025). A nutritional condition produced by a deficiency of VITAMIN D in the diet, insufficient production of vitamin D in the skin, inadequate absorption of vitamin D from the diet, or abnormal conversion of vitamin D to its bioactive metabolites. "Contrasting to our expectations, on the 28th day there was significantly lower ADAMTS13 levels in patients with normal vitamin D level vs. patients with vitamin D deficiency with median values 709 ng/mL vs. 1274 ng/mL and p-value of 0.009." (PMID 40671161, 2025).
vivax malaria (1 paper, 2015). "Plasma ADAMTS13 activity was decreased in vivax malaria, with deficiency associated with both severe disease and with impaired microvascular function." (PMID 25569250, 2015). "In vivax malaria, IL-6 was inversely correlated with ADAMTS13 activity (ρ = −0.40, P = 0.013) and platelet nadir (r = −0.44, p = 0.0009)." (PMID 25569250, 2015). "IL-6, elevated in vivax malaria, is known to be a major inhibitor of ADAMTS13 activity." (PMID 25569250, 2015).
infection (36 papers, 2011 to 2026). The state of being infected such as from the introduction of a foreign agent such as serum, vaccine, antigenic substance or organism. "In support of translational relevance, recombinant ADAMTS13 has been shown to restore neutrophil and platelet reconstitution, and reduced activity correlates with increased infection risk and mortality in BMT patients." (PMID 41051174, 2025). "Even when genetic or complement assays are limited by resource constraints, a structured diagnostic approach - integrating ADAMTS13 testing, infection exclusion, and drug history - can provide reliable evidence for clinical decision-making." (PMID 41383869, 2025). "ADAMTS13 deficiency increases inflammation and tissue injury caused by ischemia, trauma or infection." (PMID 38963011, 2024). "COVID-19 infection has been shown to be associated with a reduction in activity of ADAMTS13, which was particularly seen in those with severe infection." (PMID 39274365, 2024). "The high prevalence of infections at time of diagnosis (41%) suggest that these pathogens are at least one of the triggers involved in the loss of tolerance towards ADAMTS13." (PMID 34858410, 2021). "Although much remains to be elucidated as regard to the mechanism for the development of TMA, the decreased level of ADAMTS-13 would act in concert with other detrimental factors associated with infection and DIC to induce TMA." (PMID 24279773, 2013). "Given the pivotal role of endothelial injury in ACLF pathogenesis, biomarkers such as vWF and ADAMTS13 may enhance risk stratification and enable earlier interventions, including infection prevention, trial enrollment, and timely liver transplant evaluation." (PMID 40429533, 2025). "The subsequent clinical presentation may closely resemble TTP, which is a primary and severe ADAMTS13 deficiency, but would improve once the underlying infection is treated." (PMID 41536402, 2025). "In TTP patients, TPE duration can be influenced by disease severity, ADAMTS13 activity, infection, earlier initiation, and adjunctive therapy (rituximab)." (PMID 39518668, 2024). "Patients found to have discrepant ADAMTS13 activity results were more likely to have multiple comorbidities or concurrent active diagnoses of cancer or infection." (PMID 39124729, 2024). "D-dimers were increased while PLT count and ADAMTS-13 were found to be at lower levels in the acute phase compared to post infection and differences were statistically significant." (PMID 37886991, 2023). "ADAMTS-13 increased post infection with levels exceeding controls (618.8 ± 130.0 ng/mL vs. 577.2 ± 113.6 ng/mL, p = 0.002)." (PMID 37886991, 2023). "Coagulation factors, natural inhibitors of coagulation and ADAMTS-13 (A disintegrin and metalloprotease with thrombospondin type-1 motives) were measured in term and preterm neonates in the acute phase of infection and after recovery." (PMID 37886991, 2023). "ADAMTS-13 was decreased in the acute phase of infection in contrast to the controls (488.5 ± 75.4 ng/mL vs. 577.2 ± 113.6 ng/mL, p = 0.015)." (PMID 37886991, 2023). "What is more, ADAMTS-13 levels were positively correlated with PLT count in the acute phase of infection (r = 0.507, p = 0.045) and negatively correlated with CRP (r = −0.787, p < 0.001)." (PMID 37886991, 2023). "The pathogens’ target organs or target cells are listed, as well as one exemplary reference for each microorganism reporting a clear association between iTTP (defined as ADAMTS13 activity <10% and presence of anti-ADAMTS13 antibodies) and the infection." (PMID 34858410, 2021). "Our study suggests that ERT of ADAMTS13 with infrequent or episodic dosing, e.g. upon infection driven flares of TTP, would be technically feasible with an mRNA-based therapeutic approach." (PMID 29777164, 2018). "In this case, ADAMTS13 activity was normal, and inhibitors were absent, supporting infection-associated secondary TMA." (PMID 41551848, 2026).
infection (continued). "Our finding was revealed that ADAMTS13 level is relatively reduced during AML due to the increased inflammatory markers and infections associated with the disease course which increase the VWF multimers increasing the ADAMTS13 consumption or catabolism or inactivation by thrombin." (PMID 40671161, 2025). "Also, lower level of ADAMTS13 was found in AML patients with infection owing to the inflammatory micro-environment." (PMID 40671161, 2025). "We examined the cause of TMA, but no infections, hypocomplementemia, or reduced ADAMTS13 activity were found." (PMID 39830571, 2024). "Interestingly, after infection ADAMTS13; a von Willebrand factor; VWF cleaving enzyme is found to be decreased." (PMID 38077924, 2023). "Interestingly, a trend towards superimposed normalization of ADAMTS-13 was demonstrated post infection." (PMID 37886991, 2023). "Indeed, ADAMTS-13 levels were diminished in our patient group during the acute phase of infection in comparison to recovery, as well as in comparison to controls." (PMID 37886991, 2023). "The observed associations with either infections or vaccines in the development of iTTP have not been substantiated as of yet by a direct link to a specific pathogen antigen resembling ADAMTS13." (PMID 34858410, 2021). "Their pathogenesis is different: TTP results from a severe ADAMTS13 deficiency, which can be caused by circulating autoantibodies or ADAMTS13 mutations, while HUS is correlated to infection with ST-producing bacteria or gene mutations causing an excess of activation of the alternative pathway." (PMID 31337190, 2019). "Interestingly, the ADAMTS-13 activity level still remained low (35.5%) at the time when the patient was discharged from the hospital when her infection was clinically in complete cure." (PMID 24279773, 2013). "Notable exceptions included ADAMTS13, ICAM1, and MCP1, which showed reduced expression 2 h (ADAMTS13 and ICAM1) and 4 h (MCP1) post-infection, to below detectable levels by qPCR." (PMID 40141288, 2025). "The pathogenesis of infection-induced TMA is complex and includes direct endothelial injury, ADAMTS13 inhibition, complement activation, or a combination of these mechanisms." (PMID 39039520, 2024). "Furthermore, it is worth mentioning that increased ADAMTS-13 levels in our study population post infection may be attributed to developmental aspects of coagulation and further verify the principle that the hemostatic system is balanced and protected against thrombotic complications early in life." (PMID 37886991, 2023). "Apart from infection, the most common trigger (41% of episodes) of TTP, excessive alcohol consumption, pregnancy, drug/medication use, injury, food poisoning, and various others could also trigger TTP in individuals carrying homozygous or heterozygous mutations in the ADAMTS13 gene." (PMID 31379722, 2019). "A significant negative correlation was observed between VWF and ADAMTS-13 in the acute phase of infection (r = −0.0575, p = 0.020)." (PMID 37886991, 2023). "The severity of infection as assessed by nSOFA score was positively correlated with VWF levels in the acute phase of infection (r = 0.598, p = 0.014) and negatively correlated with ADAMTS-13 levels at the same time point (r = −0.531, p = 0.034)." (PMID 37886991, 2023). "In contrast, patients with acute decompensation/infection were excluded from our study and further adjustment for CRP did not alter the association between ADAMTS13-Act and hepatic decompensation." (PMID 37605068, 2023). "ADAMTS13 median activity level among patients without infection was 90% (range: 84%–131%) and among patients with infection was 64% (range: 42%–100%)." (PMID 23302815, 2013). "To address whether the impaired ability to clear the A. fumigatus infection in the absence of ADAMTS-13 was due to a defective PMN activation, we assessed the PMN activation status in vivo during infection, using the upregulation of CD11b for degranulation and shedding of CD62L as markers." (PMID 28775254, 2017).